IL18 (interleukin 18)
Diseases named in the same sentence as IL18 in open-access papers (continued):
Sharing a sentence is not in itself a finding about the gene and the disease.
infection (continued). "Given that SSM are an essential reservoir of IL-18 and that this cytokine was required for innate IFNγ responses in the dLN upon infection with lymph-borne bacteria, we investigated its role in our model." (PMID 29263880, 2017). "In the current study, our findings show how P. aeruginosa stimulates IL-18 and IL-1β expression in hCFs during the early stages of infection and they describe an important role for bacterial flagellin." (PMID 28469996, 2017). "The expression of IL-18 was increased to 25 – fold at days 1 and 3 post infection, but decreased to 11-fold on the next day." (PMID 28569155, 2017). "Scid and wild type BMDMs both induce IL-12 (p40) gene expression upon infection with L. monocytogenes and the addition of exogenous IL-18 rescues IFN-γ production by NK cells co-cultured with L. monocytogenes-infected Scid BMDMs." (PMID 28362262, 2017). "Our results showed that infection with the PA14 ΔflgK mutant led to reduced IL-18 and IL-1β expression by hCFs." (PMID 28469996, 2017). "When the inflammasome is assembled in cells of the innate immune system, it induces caspase-1 activation, followed by production of IL-1β or IL-18; IL-1β and IL-18 contribute to host defense during infection." (PMID 28369146, 2017). "To prove that the cytokines IL-15 and IL-18 contribute to the cytotoxic functions of NK cells after high-dose FV challenge, we neutralized both cytokines during infection." (PMID 28904191, 2017). "Concomitantly, AP-3-deficient mice exhibit higher mortality and produce less IL-1β, IL-18, and IL-17 than controls upon oral STm infection." (PMID 29253868, 2017). "IL-1β and IL-18 content in the supernatant of peritoneal macrophages following 4 h of infection (MOI = 50 or 100) was significantly higher than those in the unfected control (P < 0.05)." (PMID 28468643, 2017). "The double-stranded DNA sensor AIM2 is known to recruit ASC to trigger puncta formation in response to infection, leading to caspase-1 activation and IL-1β and IL-18 release." (PMID 28771586, 2017). "Of these cytokines, significantly increased levels of MCP-1, IFN-γ and IL18 were detected in plasmas of HIL mice infected with a 107 ffu dose of HCV at 27–8 weeks post infection." (PMID 28886065, 2017). "NleF is a potent inhibitor of mammalian caspase-4/11 and thus prevents IL-18 secretion in vitro, and it blocks caspase-11-IL-18-mediated neutrophil influx during infection." (PMID 28593173, 2017). "In our study, expression of TLR4, TLR5, NLRC4, caspase-4, and matured IL-18 and IL-1β cytokines was induced in hCFs after infection with P. aeruginosa wild-type strains." (PMID 28469996, 2017). "During infections, DCs release a variety of cytokines, such as type I IFNs, interleukin 12 (IL-12), IL-15, and IL-18, that strongly influence NK cell responses." (PMID 28904191, 2017). "The levels of IL-1α, IL-1β, IL-6, and IL-18 were unchanged or increased in Ccr2-/- mice during infection, likely reflecting increased cytokine production by other immune cell types in response to the substantial increase in bacterial load." (PMID 28384349, 2017). "Measurement of IL-18 in infected hCFs supernatants revealed levels of extracellular IL-18 of ≤0.25 pg/mL for all infection conditions, which was similar to uninfected controls (P > 0.05)." (PMID 28469996, 2017). "It is noteworthy that MAIT cells can also be activated by a combination of IL-12 and IL-18, which are released during many infections." (PMID 28632753, 2017). "The invasion process triggers the production of the pro-inflammatory cytokines IL-8, IL-1β and IL-18 that recruit immune cells to the site of infection leading to inflammation." (PMID 27145267, 2016). "As IL-18 accelerates the progress of inflammation, artificially raising IL-18 levels should enhance inflammation during the first hours of infection." (PMID 27341123, 2016).
infection (continued). "In this model, IL-18 produced by bone-marrow-derived cells was critical for mucosal pathology at days 3–5 of infection and the disease was ameliorated by daily application of the IL-18 inhibitor IL-18BP." (PMID 27341123, 2016). "IL18 together with IL-12 induces cell-mediated immunity following infection and exposure to microbial products like LPS." (PMID 27653506, 2016). "In mouse bone marrow macrophages, the AIM2 inflammasome contributes partially to the production of IL-1β and IL-18 during the infection." (PMID 27994587, 2016). "A recent study showed that both cytokines were produced during L. major infection in mice, however the consequence of IL-18 induction for infection outcome is less clear." (PMID 27009263, 2016). "Seven days after infection, the expression of IL-1β, IL-6, IL-17, IL-18, and TNF-α mRNA was significantly lower in the jejunum of COS-fed mice compared to those of controls." (PMID 28100936, 2016). "Compared with the control group, infection with B. melitensis 16M cells led to a change of the inflammatory cytokines IL-1β and IL-18 to varying degrees." (PMID 27907115, 2016). "Whereas later during the course of infection IL-18-/- mice had recovered and were free of blood in their feces, almost half of WT mice were fecal blood-positive at day 5 p.i.." (PMID 27322540, 2016). "Rickettsia induced significant secretion of IL-1β and IL-18 in vitro by infected mouse bone marrow-derived macrophages (BMMs) as early as 8–12 h post infection (p.i.)in a dose-dependent manner." (PMID 27362650, 2016). "Stimulation of macrophages with a combination of IL-12 and IL-18 prevented or blocked productive infection by HIV-1 and the expression levels of SAMHD1, at both mRNA and protein levels, were increased in IL-12/IL-18 monocyte-derived macrophages (MDMs)." (PMID 27411355, 2016). "The extremely low concentrations of cytokines that are required for this process, and the speed with which it happens, identify IL-18 as a key “first responder” at the intersection of innate and adaptive immune responses to infection." (PMID 27047490, 2016). "In conclusion, the host's IL-18 dependent innate defenses and overt tissue inflammation seem to start controlling pathogen loads only after the initial 12h of infection." (PMID 27341123, 2016). "Components of specific pathogens activate different inflammasomes, which once activated in response to pathogen-induced infection, induce the activation of caspases, and the release of mature forms of interleukin-1β (IL-1β) and IL-18." (PMID 27994587, 2016). "Later in infection, or during re-infection, after the differentiation of antigen-specific T helper cells and production of antibodies, IL-18 synergizes with IL-2 and with antibody-antigen complexes to enhance ADCC and IFN-γ production." (PMID 27047490, 2016). "The increased susceptibility of Casp1/11-/-, Asc-/-, and IL-1r1-/- mice to Ft LVS infection in this study and IL-1β-/- mice in a previous study clearly underscore the critical requirement of IL-1β/IL-18 for protective immunity." (PMID 27926940, 2016). "Infection of eWT or eK201R triggered macrophages to secrete cytokines including IL-18, IL-1β and TNF-α." (PMID 26943369, 2016). "Our previous A. butzleri infection studies in gnotobiotic IL-10−/− mice further revealed that in the colon IL-18 mRNA levels were elevated during both the early and late phase of infection, whereas colonic IL-22 mRNA was upregulated during the former only." (PMID 27385977, 2016). "Pro-inflammatory cytokines (IFN-γ, IL-18, IL-6, TNF-α) and chemokines (CCL2, CCL5, CCL7, CXCL1, CXCL10) were found to be increased in sera of ZIKV-infected mice, indicating that infection causes systemic inflammation." (PMID 27163257, 2016).
infection (continued). "IFN-γ production is controlled by cytokines secreted from antigen presenting cells (APCs), most notably IL-12 and IL-18; these cytokines serve as a bridge to link infection with IFN-γ production in the innate immune response." (PMID 26880213, 2016). "IL-18 is one of the most important pro-inflammatory cytokines in host defense against infection, and in NK cells activation." (PMID 27180811, 2016). "In response to R. australis, mouse macrophages secrete IL-1β and IL-18 as late as at 8 h p.i. after a high dose of infection and at 12 h after a low dose of infection." (PMID 27362650, 2016). "Altogether, these findings clearly point to IL-18 along with IFN-γ as crucial players in the immune response against infection by this parasite." (PMID 27027876, 2016). "One effective approach is to modulate the crosstalk between NK cells and dendritic cells, which produce NK cell-stimulating cytokines like type I interferons (IFN), IL-12, IL-15, and IL-18 upon retrovirus sensing or infection." (PMID 27821119, 2016). "In our system of acute bacterial mucosa infection, IL-18 a) upregulated NK cell recruiting chemokines at the site of infection and b) stimulated the migratory capacity of NK cells." (PMID 27341123, 2016). "In DENV infection, IL-18 levels in plasma were markedly increased during the acute phase compared to the convalescent phase of infection and healthy controls." (PMID 27337592, 2016). "Several transcriptional regulators were predicted to be significantly inhibited (e.g. IL12 and IL18) or activated (e.g. miR155-5p) in PBMC during infection." (PMID 27661612, 2016). "In contrast, the IL-18 response occurred mostly at the post-transcriptional level, as Il18 transcript levels remained unchanged at least at this early stage of the infection." (PMID 27341123, 2016). "Upon infection, they initiate inflammatory responses by releasing cytokines and chemokines, such as IL-1β, IL-18, TNF-α, and CCL3." (PMID 27043315, 2016). "It had remained unclear, if the observed delay in cecal pathology is explained either by an important function of IL-18 during early infection, or by a general alteration of mucosal homeostasis in the knockout mice." (PMID 27341123, 2016). "One group of these IL-18 dependent chemokines is known to coordinate the recruitment of neutrophils to sites of infection (depicted in green)." (PMID 27341123, 2016). "Of these, Il18 is reported to interact with Il12 to stimulate interferon gamma (IFN-γ) production from NK cells during the early host response to infection." (PMID 26779389, 2015). "IL-1β and IL-18 levels were measured in the bronchoalveolar lavage fluid (BALF) or serum obtained from infected mice 72 hours or 6 days post-infection." (PMID 25768794, 2015). "IL-1β and IL-18 are powerful proinflammatory cytokines that have been shown to be protective in a large number of experimental infection models." (PMID 25768794, 2015). "The expression of mRNA encoding several interleukins was also induced in the infected mouse uterus at 28 days post-infection, including Il1b, Il12a, Il12b, Il16, Il18, and Il27." (PMID 26779389, 2015). "The authors showed that the secretion of IL-18 is induced in DCs upon infection with H. pylori and suggest a key role for DC-derived IL-18 in skewing T cell differentiation away from Th17 and toward Treg responses." (PMID 26525279, 2015). "It has been shown that inflammatory monocytes activate both NK cells and memory CD8+ T cells through producing IL-18 and IL-15 during infection." (PMID 26468944, 2015). "In keeping with phagosomal escape as crucial to step 2 in inflammasome activation, all FPI mutant Francisella showed reduced IL-18 processing in an overnight infection model." (PMID 25993107, 2015).
infection (continued). "IL-18 mRNA expression levels were up-regulated moderately after infection, with a peak of 11-fold at 2 dpi." (PMID 25884204, 2015). "Il-18-/- mice quickly succumb to the infection and showed higher bacterial burden in organs and lower level of IFNγ in BALF and serum compared to wild type C57BL/6J mice." (PMID 25768794, 2015). "Our results demonstrate that Y. pestis activates pro-inflammatory cytokines IL-1β and IL-18 in the lung early during infection." (PMID 25781467, 2015). "This is in clear contrast to Il-18-/- mice that shows signs of morbidity and mortality in the early days of infection." (PMID 25768794, 2015). "The level of mRNA encoding 4 interleukins (Il10, Il11, Il1rn, Il1a) was increased and 1 interleukin (Il18) decreased in vaginal tissue collected at 35 days post-infection." (PMID 26779389, 2015). "Inflammasome activation is an important mediator of host inflammatory responses and has been shown to be important to controlling infection with a number of pathogens, primarily through the secretion of IL-1β and IL-18." (PMID 25781467, 2015). "On the contrary, the elevated expression of caspase-1 p10, IL-1β and IL-18 by D39 infection was further increased in response to treatment with 3-MA." (PMID 26683708, 2015). "Inoculation of WT mice with S. Typhimurium resulted in a rapid increase in IL-18 plasma concentrations in the typhoid model (from 162 pg/ml at day 2, to 627 pg/ml 5 days post infection; p = 0.02), corresponding with inflammasome activation." (PMID 25115174, 2014). "Inflammasomes are multi-protein complexes that have gained attention for their capacity to link the sensing of infection or injury with subsequent inflammatory caspase activation and ensuing cleavage and release of the inflammatory cytokines, IL-1β and IL-18." (PMID 24886384, 2014). "Infection by various microbes including Salmonella, Aspergillus, and E. coli LPS, induce iNKT cell activation by a combination of IL-12, IL-18, and/or TCR stimulation through interaction with CD1d." (PMID 24391492, 2014). "Levels of IL-18 in the liver and sera are elevated during the transition phase of the infection, when a significant expansion of MCPHT cells occurs." (PMID 24824897, 2014). "Secretion of IFN-γ is dependent on IL-18, also known as interferon gamma inducing factor, and is essential for establishing an early host resistance to infection with Salmonella." (PMID 25339955, 2014). "Expression of IL-18 was up-regulated in duck cells but was down-regulated in chicken cells following infection with H5N1-tyEng91 or H5N1-tyTR05 viruses." (PMID 25431115, 2014). "In regards to the mucosal inflammatory reactions, proinflammatory cytokines IL-1beta, IL-6, IL-15, IL-12 and IL-18 were all significantly lower in the lungs of SARS-CoV-infected aged animals at either day 5 or 10 post infection." (PMID 24642138, 2014). "The best elucidated effector mechanisms involved in the control of infections mediated by caspase-1 are the secretion of inflammatory cytokines IL-1β and IL-18 and the induction of pyroptosis." (PMID 25071770, 2014). "The NLRP3 inflammasome is the most characterized inflammasome activated by cellular infection or stress, which is responsible for the maturation of proinflammatory cytokines IL-1β and IL-18." (PMID 23942110, 2013). "These chemokines recruit NK cells at the infection site where IL-12 and IL-18 promote IFNγ production which then exerts protective immune response." (PMID 24350246, 2013). "NLRC4 plays a vital role in regulating IL-1β and IL-18 production during lung mucosal defense following infections with Pseudomonas aeruginosa and Burkholderia pseudomallei." (PMID 23577168, 2013). "In our recent study, we observed the differential responses of M-Mφ and GM-Mφ to DV, such as infection rate, and the potential ability for IL-1β and IL-18 production." (PMID 23742038, 2013).
infection (continued). "Production of IFNγ is mostly regulated by two other cytokines such as IL-12 and IL-18 which mediate IFNγ production upon infection with Mtb in cellular innate immune response." (PMID 24350246, 2013). "Aside from mediating immune response to pathogen infection, IL-1β and IL-18 play an important role in driving adaptive immunity during infection." (PMID 23742038, 2013). "In contrast the expression of IL1B and IL18 was more substantially increased, with significant fold changes in expression of IL-1β mRNA (∼20-fold, p < 0.05) and IL-18 mRNA (∼30-fold, p < 0.05) at 120 min post-infection." (PMID 24137162, 2013). "It has been confirmed that after infection of macrophages with influenza virus, cells produce IL-18, which acts synergistically with IFN-α and enhances IFN-γ synthesis." (PMID 22776696, 2012). "Macrophages and neutrophils play a key role in the initial response to infection by secreting the cytokines IL-12, IL-18, and TNF-α." (PMID 22738332, 2012). "The IL-18 gene is upregulated in the small intestine of mice in response to infection, and IL-18 mRNA and protein are upregulated in IECs infected with C. parvum in vitro." (PMID 22685452, 2012). "It was previously demonstrated that IL-18 bp was produced in response to VACV (WR strain) infection in vitro." (PMID 22384183, 2012). "Infection of BMDC by Lm induced secretion of IL-18 and IL-1β, which was significantly reduced upon infection with Δp60 Lm." (PMID 23028835, 2012). "After DENV-3 inoculation, there were detectable levels of both IL-12/23p40 and IL-18 cytokines in the spleen of WT mice already on day 5 of infection." (PMID 22666512, 2012). "The pro-inflammatory cytokine IL-18 was the only cytokine that decreased (2 fold) in expression levels in the rabbit model after infection with the virulent Shigella strain." (PMID 22675469, 2012). "We found that IL-18 bp contributes to immune response evasion during MVA infection, as the deletion enhances T-cell immune responses against vector antigens." (PMID 22384183, 2012). "IL-18 levels reduced to basal values at the 7th day of infection, while IL-12/23p40 remained above background levels at this time point (respectively)." (PMID 22666512, 2012). "We chose to block IL-18 at day 3.5 after infection to avoid affecting endogenous antiviral effects, such as the induction of IFN-γ production that contributes to the early control of MCMV infection." (PMID 22891066, 2012). "There were detectable levels of both IL-12/23p40 and IL-18 cytokines in the spleen of WT mice already on day 5 of infection." (PMID 22666512, 2012). "This study demonstrates the relevance of IL-18 bp contribution in the immune response evasion during MVA infection." (PMID 22384183, 2012). "Surprisingly, the same group also reported a deleterious role for IL-18 in this type of infection, a further indication that each pathogen displays unique virulence strategies." (PMID 22241982, 2011). "The mutant BMDMs or wild-type controlmacrophages were infected with Yp-YopJKIM or Yp-YopJC172A.Tissue culture supernatants were collected and analyzed by ELISA to measure thelevels of IL-1β and IL-18 present after 24 hr of infection." (PMID 21533069, 2011). "Measurements of cytokines in the BALF obtained from mice at 24 and 48 hours post-infection indicated that the levels of IFNγ were drastically reduced in Il-18-/- mice, a finding consistent with the established function of IL-18 as an IFNγ-inducing cytokine." (PMID 22241982, 2011). "More recently, it has been demonstrated that the AIM-2 inflammasome mediates caspase-1 activation and secretion of mature IL-1β and IL-18 during FT infection." (PMID 21819572, 2011). "High amounts of secreted IL-1β and IL-18 are detectedat 24 hr post infection under the low MOI procedure." (PMID 21533069, 2011).